MYCBP (MYC binding protein)
Description:
May control the transcriptional activity of MYC. Stimulates the activation of E box-dependent transcription by MYC.
Synonyms: AMY-1
Tractability: PROTAC: ubiquitination databases record sites on it; its protein half-life has been measured.
Gene: Protein-coding gene on chromosome 1 (38,862,493 to 38,873,378, reverse strand). Ensembl gene ENSG00000214114.
Subcellular location: Cytoplasm; Nucleus; Mitochondrion
Subcellular location (Human Protein Atlas): Nucleoplasm; Mitochondria
Gene Ontology:
Molecular function: protein binding; transcription coactivator activity
Biological process: regulation of DNA-templated transcription; spermatogenesis; positive regulation of DNA-templated transcription
Cellular component: cytoplasm; nucleus; mitochondrion
Genetic constraint (gnomAD): Loss-of-function variants: 4 observed, 12.23 expected, observed/expected ratio (o/e) 0.33, 90% interval 0.16 to 0.75. The upper end of that interval is the gene's LOEUF score, 0.75, which puts it in group 3 of 6, group 1 being the genes least tolerant of losing a copy. Missense variants: 93 observed, 98.72 expected, observed/expected ratio (o/e) 0.94, 90% interval 0.8 to 1.12. Synonymous variants: 31 observed, 34.38 expected, observed/expected ratio (o/e) 0.9, 90% interval 0.68 to 1.22.
Homologues: Orthologues: macaque MYCBP (100% identical), dog MYCBP (99% identical), pig MYCBP (99% identical), guinea pig MYCBP (97% identical), rat Mycbp (97% identical), chimpanzee MYCBP (87% identical), mouse Mycbp (85% identical), zebrafish mycbp (63% identical).
Diseases named in the same sentence as MYCBP in open-access papers:
MYCBP is named in the same sentence as 27 diseases in open-access papers, as found by Europe PMC text mining. Sharing a sentence is not in itself a finding about the gene and the disease. The quoted sentences say what the papers report.
gastric cancer (4 papers, 2019 to 2024). A primary or metastatic malignant neoplasm involving the stomach. "In esophageal cancer, miR-26a and miR-26b inhibit the proliferation of tumor cells by inhibiting the expression of MYCBP, and the overexpression of MYCBP-binding protein promotes the invasion and metastasis of gastric cancer." (PMID 37654657, 2023). "The upregulation of MYCBP promoted the invasion and migration of gastric cancer cells." (PMID 38994720, 2024). "Other studies had also identified the abnormal expression of MYC-binding protein (MYCBP) during tumorigenesis in multiple types of cancer, such as gastric cancer, colon cancer, and PC." (PMID 32850392, 2020).
glioma (4 papers, 2020 to 2024). A benign or malignant brain and spinal cord tumor that arises from glial cells (astrocytes, oligodendrocytes, ependymal cells). "Recent studies have also indicated that MYC binding protein (MYCBP) and its related lncRNAs are associated with tumorigenesis in different cancers such as colon cancer and glioma." (PMID 38994720, 2024). "Chromosome 1p co-deletion may confer better survival in patients with lower grade glioma in part because of loss of the MycBP oncogene, which is important in glioma development." (PMID 38196589, 2023). "Recently published studies show that MYCBP plays a tumor promoter role in glioma, hepatocellular carcinoma and esophageal squamous cancer." (PMID 38570856, 2024). "Patients with low MYCBP expression have better survival in low grade glioma and hepatocellular carcinoma." (PMID 38570856, 2024). "Out of the well-predicted genes, CDK4, MMP7, MYCBP, and TMEM59 in gliomas and LCP1 in RCC have been implicated in multiple cancer types." (PMID 32194984, 2020).
colon carcinoma (3 papers, 2020 to 2024). "MYCBP was identified as a target of β-catenin/lymphoid enhancer-binding factor (LEF) transcriptional regulation in colon carcinoma." (PMID 38570856, 2024).
colorectal cancer (3 papers, 2019 to 2023). A primary or metastatic malignant neoplasm that affects the colon or rectum. "This study aimed to study the association of a novel lncRNA MFI2‐AS1 with miR‐574‐5p/MYCBP axis in the development of colorectal cancer (CRC)." (PMID 31094023, 2019). "For example, the non-coding RNA MFI2-AS1 is highly expressed in colorectal cancer and promotes colorectal cancer cell proliferation, migration and invasion through the miR-574-5p/MYCBP axis." (PMID 36934264, 2023).
triple-negative breast carcinoma (3 papers, 2021 to 2024). An invasive breast carcinoma which is negative for expression of estrogen receptor (ER), progesterone receptor (PR), and human epidermal growth factor receptor 2 (HER2). "Further empirical studies have revealed that MYCBP interacts with SPAG5 enhancing c-MYC transcriptional activity in triple-negative breast cancer." (PMID 34277412, 2021). "SPAG5 interacts with MYCBP to elevate the transcriptional activity of c-MYC, thereby accelerating DNA repair and tumor growth of triple-negative breast cancer." (PMID 38807081, 2024).
breast carcinoma (2 papers, 2019 to 2020). "b Regression analysis identified a positive relationship between SPAG5 and MYCBP protein expression levels in breast cancer tissues." (PMID 30736840, 2019). "Then, we examined MYCBP expression in 183 breast cancer patients using IHC and found that MYCBP protein expression is positively correlated with SPAG5 expression in breast cancer (R = 0.218, p < 0.001), as well as in TNBC (R = 0.321, p < 0.001)." (PMID 30736840, 2019). "Furthermore, a significant positive correlation between SPAG5 and MYCBP protein expression was also observed in breast cancer and TNBC tissues in our cohort." (PMID 30736840, 2019). "Reports have indicated that MYCBP plays a key role in cancer growth and progression via c-MYC regulation in breast cancer and other cancer types." (PMID 30736840, 2019).
cervical cancer (2 papers, 2023 to 2025). A primary or metastatic malignant neoplasm involving the cervix. "Highly expressed MYCBP was associated with poorer prognosis and survival, was significantly upregulated in cervical cancer, and was more associated with HPV-infected cervical cancer." (PMID 37654657, 2023). "Collectively, our findings elucidate the previously unknown functions and mechanisms of the USP25/KIFC1/MYCBP signaling axis in CCa progression, underscoring KIFC1 as a promising therapeutic target for cervical cancer." (PMID 40379626, 2025). "The USP25/KIFC1/MYCBP signal axis detected by RT-PCR did not change the expression level of c-MYC mRNA, but affected the expression levels of c-MYC transcription targets CDK4, CDK2, cyclin D1 and cyclin E which these have been reported to be regulated by c-MYC transcription in cervical cancer." (PMID 40379626, 2025).
leukemia (2 papers, 2020 to 2024). A malignant (clonal) hematologic disorder, involving hematopoietic stem cells and characterized by the presence of primitive or atypical myeloid or lymphoid cells in the bone marrow and the blood. "Despite some research on how MYCBP‐related lncRNAs may contribute to human diseases, the exact roles of GJA9‐MYCBP in the pathophysiology of leukemia are still blanketed in mystery." (PMID 38994720, 2024).
acute myeloid leukemia (1 paper, 2021). Acute myeloid leukemia (AML) is a group of neoplasms arising from precursor cells committed to the myeloid cell-line differentiation. "Besides, a recent study reported that MYCBP was inhibited by miR-22, showing a therapeutic target potential in acute myeloid leukemia." (PMID 34277412, 2021).
cervical clear cell carcinoma (1 paper, 2023). "Herein, we used comparative analysis to screen out genes with large differences in expression between HPV-negative and HPV-positive cervical clear cell carcinoma patients, including ALKBH7, MYCBP, MZF1, RNF207, RRS1, and TUSC2." (PMID 37654657, 2023).
ovarian carcinoma (1 paper, 2022). A malignant neoplasm originating from the surface ovarian epithelium. "HEK293 cells derived exosomes delivered exogenous miR-22 enhanced the radiosensitivity of ovarian cancer by inhibiting the expression of c-MyC binding protein (MYCBP) and human telomerase reverse transcriptase (hTERT)." (PMID 35915054, 2022).
tumor (19 papers, 2011 to 2025). "Our data reveal another mechanism through which miR-22 might act as a tumor suppressor: loss of miR-22 expression not only permits an increase in MYCBP but also an increase in HIF-1α." (PMID 21629773, 2011). "After overexpression of KIFC1 and MYCBP in HeLashUSP25, the tumor growth rate was also significantly accelerated compared with that in the empty vector group." (PMID 40379626, 2025). "After MYCBP was overexpressed in HeLaKIFC1-/-, the tumor growth rate was accelerated compared with the empty carrier group, and the expression levels of ki-67 and MYCBP in tumor tissues were significantly upregulated." (PMID 40379626, 2025). "The expression level of MYCBP was also significantly up-regulated in tumor tissues of HeLashUSP25+KIFC1 OE." (PMID 40379626, 2025). "In general, these findings imply that LINC00665 functions as a miR-195-5p sponge, regulating MYCBP expression and promoting tumor growth in LUAD." (PMID 34277412, 2021). "In conclusion, our study revealed that lncRNA MFI2‐AS1 and MYCBP were up‐regulated in CRC tumour tissues when compared with non‐tumour control tissues." (PMID 31094023, 2019). "We determined the up‐regulated expression of MYCBP protein in CRC tumour tissues by comparing with adjacent tissues." (PMID 31094023, 2019). "SPAG5 promoted tumor growth and decreased cell sensitivity to PARPi via the MYCBP/c-MYC pathway in TNBC." (PMID 30736840, 2019). "LncRNA MFI2‐AS1 and MYCBP were up‐regulated in CRC tissues when compared with adjacent non‐tumour tissues." (PMID 31094023, 2019). "MiR‐22 acts as a tumor suppressor through direct repression of MYCBP expression and subsequent reduction in oncogenic c‐Myc activities." (PMID 29719937, 2018). "Among them, SSRP1 and SEPT2 that participate in cell cycle progression or MYCBP, HMGA1 and MT2A involved in cell growth and proliferation and previously linked to tumor progression." (PMID 24870930, 2014). "Mir-22 functions as a tumor suppressor by targeting Myc Binding Protein (MYCBP)." (PMID 40124331, 2025). "Moreover, MYCBP is the target gene for several miRNAs and enrolled in tumor progression through binding miRNAs, such as miR-495-3p, miR-574-5p and miR-26b-5p." (PMID 38570856, 2024). "The MYCBP/c-MYC pathway plays an important role in tumor development." (PMID 38570856, 2024). "Furthermore, we demonstrated that SPAG5 promoted tumor growth by increasing c-MYC transcriptional activity via interaction with MYCBP." (PMID 30736840, 2019). "This tumor suppressor activity of miR-22 involves repression of MYCBP." (PMID 21629773, 2011). "SPAG5 promotes tumor growth and DNA repair by increasing c-MYC transcriptional activity via interaction with MYCBP." (PMID 30736840, 2019). "We found that both MYCBP and MFI2‐AS1 were up‐regulated in CRC tissues when compared with adjacent non‐tumour tissues." (PMID 31094023, 2019). "It has been also demonstrated that the normal function of this tumor suppressor miRNA is to down-regulate a number of putative oncogenes including validated miR-22 targets MAX, MYCBP, HDAC4, HDAC6, CDK6, CDKN1A and NCoA1." (PMID 29716630, 2018). "The results from the screen uncovered MYCBP as a target in sensitizing ALK+ NSCLC to crizotinib, implicating the MYC signaling axis as critical in this tumor type." (PMID 29507657, 2018). "We further demonstrate that normal function of this tumor suppressor microRNA is to down-regulate a number of putative oncogenes including validated miR-22 targets MAX, MYCBP, HDAC4, HDAC6, CDK6, and NCoA1." (PMID 26244872, 2015). "Analysis of the tumor TCGA database revealed that transcription levels of MYCBP in CCa tumor tissues were higher than in adjacent non-tumor tissues." (PMID 40379626, 2025). "Thus, to confirm the relevance of miR-888-5p as post-transcriptional regulator of MYCBP gene, we analyzed miRNA levels and gene expression profiles in a TCGA cohort of head and neck squamous carcinoma (HNSC) tumor patients." (PMID 33297397, 2020).
cancer (10 papers, 2015 to 2025). A tumor composed of atypical neoplastic, often pleomorphic cells that invade other tissues. "As the target gene of long noncoding RNA (lncRNA), MYCBP can promote the occurrence and development of cancer under the regulation of lncRNA." (PMID 37654657, 2023). "Most of the miR-22-regulated targets involved in carcinoma development pathway were recently validated, including MYCBP, MCM7, CDC25C, and CCNA2, all of which are responsible for the cell proliferation." (PMID 27738335, 2016). "Downregulation of MYCBP has been shown to inhibit cancer cell migration, invasion, and metastasis." (PMID 40801055, 2025). "An accumulating evidence has verified that the aberrant expression of MYCBP‐related lncRNAs may play important roles during cancer development." (PMID 38994720, 2024). "Multiple studies have shown that MYCBP plays an oncogenic role in most cancers." (PMID 37654657, 2023). "Transfection of malignant T cells with recombinant miR-22 inhibits the expression of validated miR-22 targets including NCoA1, a transcriptional co-activator in others cancers, as well as HDAC6, MAX, MYCBP, PTEN, and CDK2, which have all been implicated in CTCL pathogenesis." (PMID 26244872, 2015). "Overall, we found that ALKBH7, MYCBP, MZF1, RRS1, and TUSC2 were reported to be involved in the development and progression of cancer." (PMID 37654657, 2023). "Altogether, ALKBH7, MYCBP, MZF1, RRS1, and TUSC2 were reported to be involved in the development and progression of cancer, and dysregulation of these genes was known to be highly correlated with tumorigenesis." (PMID 37654657, 2023). "Interestingly, MYCBP is the binding protein of MYC, an important oncogene well characterized in cancer." (PMID 33327559, 2020).
infection (1 paper, 2021). The state of being infected such as from the introduction of a foreign agent such as serum, vaccine, antigenic substance or organism. "The MYCBP gene, which controls the transcriptional activity of the proto-oncogene MYC and that plays a role in cell cycle progression, apoptosis and cellular transformation, was the only gene down-regulated in common to all infection settings." (PMID 33503840, 2021).
MYCBP also shares sentences with these, for which no sentence is quoted: hepatocellular carcinoma (3 papers); acute lymphoblastic leukemia (1); ameloblastoma (1); esophageal cancer (1); esophageal squamous cell carcinoma (1); lung adenocarcinoma (1); lung carcinoma (1); nervous system cancer (1); Obesity (1); osteosarcoma (1); steatosis (1); tuberculosis (1); type 2 diabetes mellitus (1).